RN7SKP176 (RN7SK pseudogene 176)
Gene: Miscellaneous RNA gene on chromosome 16 (81,961,926 to 81,962,243, forward strand). Ensembl gene ENSG00000260682.
Homologues: Orthologues: chimpanzee 7SK (97% identical). Paralogues in human: 7SK (82% identical), RN7SKP203 (80% identical), RN7SKP255 (79% identical), RN7SKP9 (78% identical), RN7SKP180 (78% identical), RN7SKP71 (77% identical), RN7SKP246 (77% identical), RN7SKP8 (77% identical), RN7SKP243 (76% identical), RN7SKP187 (76% identical), RN7SKP47 (76% identical), RN7SKP79 (76% identical), and 283 more.